PPIP5K1 (diphosphoinositol pentakisphosphate kinase 1)
Description:
Bifunctional inositol kinase that acts in concert with the IP6K kinases IP6K1, IP6K2 and IP6K3 to synthesize the diphosphate group-containing inositol pyrophosphates diphosphoinositol pentakisphosphate, PP-InsP5, and bis-diphosphoinositol tetrakisphosphate, (PP)2-InsP4. PP-InsP5 and (PP)2-InsP4, also respectively called InsP7 and InsP8, regulate a variety of cellular processes, including apoptosis, vesicle trafficking, cytoskeletal dynamics, exocytosis, insulin signaling and neutrophil activation. Phosphorylates inositol hexakisphosphate (InsP6) at position 1 to produce PP-InsP5 which is in turn phosphorylated by IP6Ks to produce (PP)2-InsP4. Alternatively, phosphorylates PP-InsP5 at position 1, produced by IP6Ks from InsP6, to produce (PP)2-InsP4. Activated when cells are exposed to hyperosmotic stress.
Synonyms: hsVIP1; HISPPD2A; IP6K; IPS1; KIAA0377; VIP1
Tractability: Antibody: UniProt places it where antibodies can reach, with high confidence; its Gene Ontology location is reachable by antibodies, with high confidence; the Human Protein Atlas places it where antibodies can reach. PROTAC: ubiquitination databases record sites on it; its protein half-life has been measured.
Target class: Enzyme
Gene: Protein-coding gene on chromosome 15 (43,533,462 to 43,590,228, reverse strand). Ensembl gene ENSG00000168781.
Subcellular location: Cytoplasm, cytosol; Cell membrane
Subcellular location (Human Protein Atlas): Cytosol; Plasma membrane
Pathways (Reactome):
Metabolism: Synthesis of pyrophosphates in the cytosol
Gene Ontology:
Molecular function: 5-diphosphoinositol pentakisphosphate 1-kinase activity; inositol hexakisphosphate 1-kinase activity; inositol hexakisphosphate 5-kinase activity; inositol hexakisphosphate kinase activity; inositol-1,3,4,5,6-pentakisphosphate kinase activity; ATP binding; diphosphoinositol pentakisphosphate kinase activity
Biological process: inositol metabolic process; inositol phosphate metabolic process
Cellular component: cytosol; plasma membrane
Genetic constraint (gnomAD): Loss-of-function variants: 8 observed, 18.85 expected, observed/expected ratio (o/e) 0.42, 90% interval 0.25 to 0.77. The synonymous counts are far from expectation, so gnomAD's model fits this gene poorly and the ratio says little. Missense variants: 378 observed, 490.67 expected, observed/expected ratio (o/e) 0.77, 90% interval 0.71 to 0.84. Synonymous variants: 143 observed, 188.69 expected, observed/expected ratio (o/e) 0.76, 90% interval 0.66 to 0.87.
Homologues: Orthologues: chimpanzee PPIP5K1 (95% identical), pig PPIP5K1 (92% identical), rat Mfap1a (90% identical), dog PPIP5K1 (90% identical), mouse Ppip5k1 (87% identical), rabbit PPIP5K1 (87% identical), guinea pig PPIP5K1 (84% identical), tropical clawed frog ppip5k1 (64% identical), zebrafish ppip5k1a (64% identical), zebrafish ppip5k1b (58% identical), Drosophila melanogaster l(1)G0196 (48% identical), Caenorhabditis elegans F46F11.1 (38% identical). Paralogues in human: PPIP5K2 (56% identical).
Diseases named in the same sentence as PPIP5K1 in open-access papers:
PPIP5K1 is named in the same sentence as 26 diseases in open-access papers, as found by Europe PMC text mining. Sharing a sentence is not in itself a finding about the gene and the disease. The quoted sentences say what the papers report.
melanoma (1 paper, 2014). A malignant, usually aggressive tumor composed of atypical, neoplastic melanocytes. "For example PPIP5K1->CATSPER2 and YARS2->NAP1L1 have been predicted in melanoma samples." (PMID 25133550, 2014).
infection (10 papers, 2013 to 2025). The state of being infected such as from the introduction of a foreign agent such as serum, vaccine, antigenic substance or organism. "It is therefore significant that we also found silencing of IPPK, PPIP5K1 and PPIP5K2 dampened IFNβ transcription during infection of HEK293 cells by Sendai virus (SeV), a known stimulator of RIG-I." (PMID 24586175, 2014). "Detailed genetic and biochemical experiments demonstrated that the kinase activities of IPPK, PPIP5K1 and PPIP5K2 (which convert IP5 to1-IP7) were critical for both interferon induction, and the control of cellular infection by Sendai and influenza A viruses." (PMID 24586175, 2014). "Furthermore, we also found that HEK293 cells were more resistant to infection with influenza A virus upon over expression of either IPPK, PPIP5K1 or PPIP5K2." (PMID 24586175, 2014).
tumor (2 papers, 2016 to 2022). "Our observations that PPIP5K1 binds to the exocyst complex, RalA, and has anti-apoptotic properties suggest a possible link between PPIP5K and Ral GTPase-mediated tumor development." (PMID 31051014, 2016).
PPIP5K1 also shares sentences with these, for which no sentence is quoted: Obesity (5 papers); chronic kidney disease (4); hyperphosphatemia (3); metabolic disease (3); osteoporosis (3); Alzheimer disease (2); cancer (2); fatty liver disease (2); Hyperglycemia (2); Insulin resistance (2); diabetes (1); hearing loss (1); Hepatic steatosis (1); hyperlipidemia (1); Infertility (1); kidney damage (1); lung carcinoma (1); male infertility (1); mood disorder (1); pneumonia (1); psychiatric disease (1); thrombosis (1); viral infections (1).